PON1 (paraoxonase 1)
Diseases named in the same sentence as PON1 in open-access papers (continued):
Sharing a sentence is not in itself a finding about the gene and the disease.
cardiovascular disease (continued). "The PON-1 and PON-2 genes are part of the same genetic cluster on human chromosome 7, and their respective polymorphisms—L55M, Q192R, A148G, and C311S—have been linked to the development of various metabolic disorders, particularly those related to lipid metabolism and cardiovascular diseases." (PMID 40002395, 2025). "Compounds 7.4.12–14 exhibited moderate inhibition of PON1 with IC50 values of 0.832, 1.11, and 0.701 mM, respectively, and the inhibition of PON1 led to the increase of oxidative stress and oxidized low density lipoproteins, which enhances the risk of cardiovascular disease." (PMID 32759739, 2020). "In this work the absence of a control group inhibits us to state if PON1 55 polymorphism could be responsible for the onset of cardiovascular disease." (PMID 22536511, 2012). "Functional genomic analysis is required for adequate risk assessment; an individual may be screened for all known polymorphisms of PON1, but still not be assigned a risk category for cardiovascular disease." (PMID 22536488, 2012). "In recent years, significant progress has been made in understanding the roles of oxidative stress-related enzymes, particularly paraoxonase 1 (PON1) and arylesterase (ARE), in cardiovascular disease." (PMID 39459504, 2024). "Paraoxonase 1 (PONS1) is involved in the hydrolysis of HDL particles, and the beneficial effects of HDL in cardiovascular disease is partly attributed to PONS1." (PMID 39457433, 2024). "Nonetheless, the dual functionality of BWA in activating PON-1 within HDL and inhibiting LDL oxidation indicates the efficacy of BWA against cardiovascular disorders that require a comprehensive investigation in the future." (PMID 38248328, 2024). "Extensive research has been carried out to understand and elucidate the mechanisms of paraoxonase 1 (PON1) in the development of diseases including cancer, cardiovascular diseases, neurological diseases, and inflammatory diseases." (PMID 35453382, 2022). "PON1 provides HDL antioxidant activity and inhibits the oxidation of low-density lipoproteins, playing an important role in prevention of cardiovascular diseases." (PMID 34762786, 2021). "The results show the participation of both PON1 and LOX in the pathogenesis of cardiovascular diseases play a significant role in men with type II obesity." (PMID 31737129, 2019). "At present, among several biomarkers, urinary 8-OHdG and 8-oxoGuo, serum PON1 and HO1 seem to be the most promising for predicting cardiovascular disease in T2DM." (PMID 31214280, 2019). "In this study, we evaluated the profile of several indices of PON1 and oxidative status and their relationship with CIMT, which is a marker of subclinical cardiovascular disease." (PMID 24799979, 2014). "A Japanese study showed that PON1 rs662 and rs854560 exerted no impact on cardiovascular disease (CVD) mortality in 81 HD patients." (PMID 34593900, 2021). "PON1 level and activity are reportedly predictors of cardiovascular diseases, whereas PON1 genotype was not." (PMID 32214403, 2020). "PON1 is an enzyme with strong anti-oxidative properties that is primarily associated with HDL, but its role in cardiovascular disease is not undisputed." (PMID 21711511, 2011). "There is no consensus regarding the optimal substrate to measure PON1 activity in relation to cardiovascular diseases." (PMID 21543280, 2011). "Moreover, our finding that a higher pPON1 within HDL2a was inversely associated with sdLDL in the control group suggests that a preponderance of sdLDL particles diminished the PON1 within the HDL2a subclasses, even in the absence of cardiovascular disease." (PMID 37298334, 2023). "Decreased serum PON1 activities have been reported in several diseases that have an infectious or inflammatory component, including bacterial infections, and non-communicable diseases such as chronic liver diseases, cardiovascular diseases, and cancer." (PMID 35883435, 2022).
cardiovascular disease (continued). "However, serum PON1 activities were similar in subjects with and without studied cardiovascular diseases, independently on gender." (PMID 33762698, 2021). "Collectively, such evidence suggests that non-genetic modulators of PON1 enzyme activity may also modulate cardiovascular disease and mortality risks through their effects on PON1." (PMID 24682159, 2014).
cancer (97 papers, 2005 to 2026). A tumor composed of atypical neoplastic, often pleomorphic cells that invade other tissues. "In this study, PON1 was associated with favorable prognosis, highlighting its heterogeneous role across different cancers." (PMID 41523581, 2026). "Together these data indicate that PON1, oxidative stress, chronic inflammation, and cancer can be closely linked." (PMID 41303537, 2025). "Decreased serum PON1 activity in cancer patients has been associated with tumor stage and prognosis." (PMID 40918463, 2025). "The PON1 L55M variant (rs854560) appears to be associated with overall cancer risk, particularly in breast cancer and hematological cancers." (PMID 41303537, 2025). "The dysregulation of these processes by attenuated PON1 protein/activity levels can account for PON1’s association with cardiovascular and neurological diseases and cancer." (PMID 39594433, 2024). "The latest study in renal cell carcinoma has revealed that its progression was associated with the hypermethylation of the PON1 gene, while its demethylation significantly decreased the proliferation, migration and invasion of cancer cells." (PMID 36833509, 2023). "Recently, the correlation between PON1 activity with the risk of cancer recurrence after radiotherapy (RT) has been investigated for prostate cancer (PCa) patients." (PMID 36833509, 2023). "We have shown previously that RT was associated to an increase in serum PON1 levels in cancer patients." (PMID 33886674, 2021). "Of the PON1 polymorphisms, PON1 rs662 and rs854560 are most widely studied for their association with susceptibility to different cancers." (PMID 34452542, 2021). "Consistent with what has been highlighted in this review is that decreased serum PON1 activity is associated with inflammation in cancer." (PMID 34356595, 2021). "A number of studies have shown that PON1 activity is associated with the progression of many cancers." (PMID 34819088, 2021). "Low activity of PON1 will result in excess reactive oxygen species expose individuals to higher oxidative stress and increases risk of cancer 20,21." (PMID 33046970, 2020). "A recent meta-analysis has shown a consistent association between cancer and lower serum PON1 activities, so it is important to study both PON1 and HDL subclasses in this condition." (PMID 31234489, 2019). "Lower activity of PON1 was already associated with several types of cancer, namely lung, pancreatic, gastric, colorectal, and ovarian cancer." (PMID 31430977, 2019). "In all genetic models, a significant association between PON1-L55M polymorphisms and overall cancer risk was observed." (PMID 31467900, 2019). "The cause of these differences between diseases or types of cancer cannot be deduced from the present study, but it is feasible that different factors that induce cancer produce different effects in the synthesis of PON1." (PMID 31295833, 2019). "Nevertheless, in the PON1-Q192R polymorphism, we also observe a reduced risk of the overall cancers in the allele contrast and dominant models." (PMID 31467900, 2019). "Despite the association between PON1 (Q192R and L55M) gene polymorphism and cancer risk which has been studied in detail, we should note some limitations at the same time." (PMID 31467900, 2019). "Secondly, we included more qualified studies and larger sample size, which indicates that we are relatively more accurate in assessing that association between the PON1 gene SNPs and the risk of cancer." (PMID 31467900, 2019). "The ability of PON1 detoxification of carcinogenic oxidative stress products makes it possible for researchers to predict PON1 gene polymorphism in cancer susceptibility." (PMID 31467900, 2019). "In the future, more case-control studies focusing on the relationship of PON1 rs662 C>T polymorphism with cancer risk should be performed to confirm these potential associations." (PMID 29254148, 2017).
cancer (continued). "Paraoxonase-1 (PON1) gene polymorphisms have been closely associated with the development of advanced cancers while PON1 secretion to the serum is linked with inhibition of oxidized high-density lipoprotein by its antioxidative function." (PMID 28467805, 2017). "Recent investigations have suggested that paraoxonase-1 (PON1) plays a significant role in the molecular disorders associated with cancer." (PMID 29176871, 2017). "Recently, the association between the decreased risk of cancer and PON1 rs662 C>T polymorphism was also found in Asians." (PMID 29254148, 2017). "Our understanding of the molecular basis of PON1-implicated cancer pathogenesis has been limited by the scarcity of mechanistic studies that look beyond PON1 genetic polymorphisms and enzyme activity." (PMID 28467805, 2017). "Association of PON1 to tumor development has been limited to the occurrence of its non-synonymous gene polymorphisms in cancer patients." (PMID 28467805, 2017). "The function of PON1 is anticipated in cancer disease models since it is found that certain PON1 genotypes were prone to be a cancer risk factor such as the occurrence of single nucleotide polymorphisms (SNPs) in variant alleles of PON1." (PMID 28467805, 2017). "In 2013, based on 217 confirmed cases and 217 cancer-free controls, Akkiz et al26 firstly reported the association of PON1 rs662 polymorphisms with HCC risk in the Turkish population." (PMID 26632904, 2015). "The role of PON1 in dealing with oxidative stress, inflammation, and detoxification makes it biologically plausible that variation in PON1 could affect cancer risk." (PMID 41303537, 2025). "Lower PON1 activity has been associated with several types of cancer, including GC." (PMID 38584705, 2024). "Some PON1 polymorphisms may contribute to an increased cancer risk associated with pollution and other environmental chemicals." (PMID 36829771, 2023). "Increased susceptibility to some cancers is suspected to be related to PON1 polymorphic variants." (PMID 36833509, 2023). "The epigenetic regulation of PON1 is directly linked to the presence of cardiometabolic alterations and those involving oxidative stress processes that can also be related to the presence of cancer in different tissues." (PMID 35453382, 2022). "Oxidative stress and lipid peroxidation products play a role in oncogenesis, which may suggest that PON1 is associated with cancer." (PMID 35204228, 2022). "The data suggest that PON1, oxidative stress, chronic inflammation, and cancer are closely linked." (PMID 35453382, 2022). "There are numerous studies linking PON1 with the risk of cancer, including PCa." (PMID 35204228, 2022). "Some hypotheses can be advanced to explain the molecular mechanisms likely implicated in the cancer-related decrease of serum PON1 activities in BC patients." (PMID 34696795, 2021). "It is still unclear whether the observed decrease in PON1 activity in CRC patients is causally related to cancer development or whether it is merely a reflection of cancer-induced metabolic changes." (PMID 33805921, 2021). "On the other hand, several studies also investigated the role of PON1 polymorphisms in cancer risk." (PMID 33425072, 2020). "Therefore, we conducted a meta-analysis of all eligible case-control studies to assess the association between PON1 (Q192R and L55M) gene polymorphisms and risk of cancer." (PMID 31467900, 2019). "Similarly, a significantly increased risk of the overall cancers under the homozygote, allele contrast, recessive, and dominant models was uncovered in hematological tumor in the PON1-L55M polymorphism." (PMID 31467900, 2019). "Besides, we disposed a total of 7 cancer types when dealing with PON1-L55M polymorphism nearly like PON1 Q192R polymorphism." (PMID 31467900, 2019). "Previous meta-analysis also reported the association of PON1 polymorphism with cancer risk." (PMID 31467900, 2019).
cancer (continued). "Furthermore, several variants of PON1, including Q192R and L55M, have been found to be a biologically reasonable candidate which has an obvious influence on cancer." (PMID 31467900, 2019). "However, most of the epidemiologic and molecular studies focused on the relationship of PON1 polymorphisms with the risk of cancer in Caucasians." (PMID 29254148, 2017). "In other malignancies, PON1 being part of an endogenous free radical scavenging system has been observed to be a regulator of its expression and risk factor value in various human cancers of the endometrium, ovary, stomach, and pancreas." (PMID 28467805, 2017). "Paraoxonase 1 (PON1), a liver-induced glycoprotein enzyme responsible for antioxidant defense against reactive oxygen species and anti-inflammatory, has been linked to various cancers." (PMID 26632904, 2015). "The activity of paraoxonase 1 (PON1), an antioxidant enzyme whose polymorphisms have been associated with cancer risk, may be associated with metals exposure." (PMID 24682159, 2014). "It has been emphasized that PON1 polymorphisms might contribute to the increased risk of cancer in associated with pollutants and other environmental chemicals." (PMID 17362500, 2007). "Some studies have established a positive correlation between PON1 mutations and the risk of cancer." (PMID 17362500, 2007). "As for the PON1 gene, it is known that oxidative stress, which occurs in free superoxide radical aggregation, membrane lipid oxidation, and DNA damage, is associated with cancer pathogenesis, and PON1 is responsible for the elimination of various toxins and carcinogens." (PMID 40362292, 2025). "Additionally, polymorphism genetics of the PON1 gene have been implicated in cancer development." (PMID 35453382, 2022). "In addition, PON1 polymorphisms and their association with various cancers have also been studied, although more research showing the importance of PON1 polymorphisms in cancer development is required." (PMID 36290747, 2022). "Therefore, it is reasonable to believe that the decreased activity of PON1 may be associate with the development of cancer." (PMID 29254148, 2017). "Along this line, PON1 was described as a potential novel atrokine for cancer cachexia and indicates localized inflammation in atrophying muscles." (PMID 41575592, 2026). "PON1 has been described playing a protective role in several physiological contexts including cancer, ageing and inflammatory diseases." (PMID 41181110, 2025). "Decreased NAPPs, such as albumin and PON-1, can be attributed to different mechanisms: albumin synthesis is downregulated as the liver prioritizes acute phase protein production, and its reduction may be further exacerbated by cancer-associated cachexia development." (PMID 40559770, 2025). "In our previous study, paraoxonase 1 was identified as a marker of short-term death with cancer recurrence." (PMID 39519412, 2024). "It was suggested that cancer cells are able to utilize PON1’s capability to penetrate cells in its active form as one of the apoptosis resistance mechanisms in neoplastic transformation processes." (PMID 36833509, 2023). "Each gene in the risk evaluator, PLXNA1, MARCKSL1, IQGAP3, PFN2, PON1, and TAK, has been reported to be associated with the prognosis or progression of cancer." (PMID 37954858, 2023). "Core fucosylation impacts PON1 folding and stability prior to secretion in therapy-resistant cancer cells." (PMID 36961502, 2023). "Taken together, these results suggest that core fucosylated PON1 is a major component of the constitutive N-glycome of the cancer TIS and a signature of targeted therapy resistance." (PMID 36961502, 2023). "To quantitatively validate secretome PON1 fucosylation in drug-stressed cancer cells and DR clones, we employed PON1 fucosylation-specific hybrid lectin ELISA (HLE)." (PMID 36961502, 2023). "It is worth noting that oxidative stress, PON1, inflammation, and cancer development are strictly interconnected." (PMID 37047193, 2023).